MYCNOS (MYCN opposite strand)
Description:
Regulates stability of MYCN in neuroblastoma cells by inhibiting GSK3B-mediated MYCN phosphorylation. Inhibits GSK3B activity by promoting its phosphorylation at 'Ser-9'.
Synonyms: NCYM; N-CYM; MYCN-AS1; NYCM
Gene: Long non-coding RNA gene on chromosome 2 (15,918,350 to 15,943,052, reverse strand). Ensembl gene ENSG00000233718.
Subcellular location: Cytoplasm; Nucleus
Diseases named in the same sentence as MYCNOS in open-access papers:
MYCNOS is named in the same sentence as 20 diseases in open-access papers, as found by Europe PMC text mining. Sharing a sentence is not in itself a finding about the gene and the disease. The quoted sentences say what the papers report.
neuroblastoma (23 papers, 2009 to 2025). Neuroblastoma (NB) is the most common solid, extracranial childhood tumor. "MYCNOS upregulation is associated with poor prognosis in neuroblastoma patients." (PMID 38895621, 2024). "Conversely, ncRNA MYCNOS was shown to be important in recruiting CTCF to the MYCN promoter in neuroblastoma cell lines, whereas eRNAs recruit CTCF to the boundary of the INK4a/ARF TAD in HeLa cells." (PMID 41296854, 2025). "With regard to MYCNOS, it has been reported to affect the growth of neuroblastoma cells by facilitating MYCN protein levels." (PMID 35832170, 2022). "For example, lncRNA MYCNOS upregulates MYCN expression in neuroblastoma by recruiting CTCF to promoter region of this gene to induce chromatin remodeling." (PMID 32719429, 2020). "Consistent with the literature, MYCN-amplified neuroblastoma cell lines showed very high levels of N-Myc, MYCNOS, and IGF2BP1 and very low levels of c-Myc RNA expression." (PMID 31690716, 2019). "mRNA expression levels of MYCN, ΔMYCN and MYCNOS were measured in 16 human neuroblastoma samples by QPCR relative to three reference genes: GUSB, TFRC and RNFIII." (PMID 19615087, 2009). "In addition, CCCTC-binding factor (CTCF) cooperates with noncoding RNA MYCNOS to promote neuroblastoma progression through facilitating MYCN expression." (PMID 36539767, 2022). "MYCNOS promotes the invasion and metastasis of neuroblastoma and rhabdomyosarcoma by regulating MYCN protein and may participate in the development of WT." (PMID 33718161, 2021). "Interestingly MYCN opposite strand (MYCNOS), a non-coding RNA surrounding the MYCN promoter implicated in MYCN upregulation in neuroblastoma, was also upregulated in our SCLC samples." (PMID 32224870, 2020). "Another case involves NCYM (or MYCNOS), the anti-sense gene of MYCN, serving a specific function of inhibiting GSK3β and stabilizing MYCN in human neuroblastomas." (PMID 39088850, 2024). "An alternative transcript of MYCNOS, MYCNOS-01, post-transcriptionally regulates MYCN levels and affects growth in MYCN-amplified rhabdomyosarcoma and neuroblastoma cells." (PMID 29466962, 2018). "Reduction of MYCNOS-01 or MYCN expression decreased cell growth in MYCN-amplified alveolar rhabdomyosarcoma and neuroblastoma cell lines." (PMID 29466962, 2018). "MYCNOS-01, MYCNOS-02 and MYCN expression levels were assessed in alveolar rhabdomyosarcoma and neuroblastoma cell lines and tumor samples from patients using Affymetrix microarray data and quantitative RT-PCR." (PMID 29466962, 2018). "MYCNOS and SLC30A3 were confirmed to be correlated with the status of expression of MYCN in neuroblastoma." (PMID 20380745, 2010). "The five genes identified as candidate genes involved in neuroblastoma progression were: MYCN (neuroblastoma derived), NPW (neuropeptide W), SLC30A3 (solute carrier family 30, member 3), MYCNOS (neuroblastome derived opposite strand), and MYCN* (v-myc myelocytomatosis viral related oncogene)." (PMID 20380745, 2010). "Here our RNA sequencing analysis identifies N-Myc, MYCNOS, IGF2BP1, lncNB1, RNF217, RP11-102F4.3, GRIK3, and SLCO5A1 as the RNAs most considerably over-expressed in MYCN-amplified, compared with MYCN-non-amplified, neuroblastoma cell lines." (PMID 31690716, 2019).
hepatocellular carcinoma (6 papers, 2021 to 2024). A malignant tumor that arises from hepatocytes. "For example, MYCNOS, which is upregulated in hepatocellular carcinoma cells and tissues, affects disease progression, shortens patient survival and acts as an endogenous sponge of miR-216b, thereby regulating the expression of FOXM1 and promoting the proliferation of glioblastoma cells." (PMID 38895621, 2024). "Additionally, MYCNOS was closely related to the poor prognosis of hepatocellular carcinoma based on bioinformatics analysis." (PMID 35585970, 2022). "MYCNOS also functions as an oncogenic role in promoting GBM cell proliferation and hepatocellular carcinoma invasion." (PMID 35874989, 2022).
glioblastoma (3 papers, 2022 to 2024). The most malignant astrocytic tumor (WHO grade IV). "MYCNOS, as an antisense RNA of coding gene MYCN, can play a role in the regulation of malignant tumors such as ovarian cancer 46, nephroblastoma 47, glioblastoma 48 and liver cancer 49 by regulating MYCN or other encoding genes." (PMID 37859811, 2023). "It is upregulated in glioblastoma where it might promote tumor cell proliferation via the MYCNOS/miR-216B/FOXM1 axis." (PMID 35585970, 2022).
liver cancer (2 papers, 2022 to 2023). An epithelial or non-epithelial malignant neoplasm that arises from the liver. "The lncRNA MYCNOS accelerated the proliferation and invasion of liver cancer by regulating miR-340." (PMID 36276278, 2022).
ovarian carcinoma (2 papers, 2013 to 2023). A malignant neoplasm originating from the surface ovarian epithelium. "Thus, we discovered many unproven pyroptosis related regulatory axes in ovarian cancer, such as KRT7-AS—has-miR-205—GSDMC, LINC01094—has-miR-330-3p—IRF1, ZNF32-AS2—has-miR-214—GSDME, and MYCNOS—has-miR-150—NLRP1." (PMID 37859811, 2023).
retinoblastoma (1 paper, 2020). A malignant tumor that originates in the nuclear layer of the retina. "Expression levels of all five MYCNOS variants were examined in retinoblastoma tissues compared with adult retina, retinal organoids, and the Y79 retinoblastoma cell line." (PMID 33270844, 2020). "Our findings indicate that MYCNOS coding for MYCNOS1 has a pathogenic consequence of MYCN amplification in MYCN-driven retinoblastoma." (PMID 33270844, 2020). "Here, we characterize the expression profile of all five MYCNOS variants in human retinoblastoma tissues, cell lines, retina, and retinal organoids." (PMID 33270844, 2020). "Thus, we attempted to identify MYCNOS variants in retinoblastoma and aimed to decipher the role of MYCNOS variant 1 (MYCNOS1) on the activity of MYCN-amplified retinoblastoma." (PMID 33270844, 2020). "The profiles of MYCNOS variants and MYCN status were determined in 17 retinoblastoma tissues, cell lines, retinas, and retinal organoids." (PMID 33270844, 2020). "Simultaneous expression of MYCNOS with MYCN may be needed to imitate human MYCN-driven retinoblastoma without the loss of RB1 in generating a mouse model." (PMID 33270844, 2020). "MYCNOS encodes several RNA variants whose functions have not been elucidated in retinoblastoma." (PMID 33270844, 2020). "MYCNOS (MYCN opposite strand) is co-amplified with MYCN in pediatric cancers, including retinoblastoma." (PMID 33270844, 2020). "MYCNOS appears to play a key role in cancer progression, but whether it acts as a silent passenger or is a pathogenic consequence of MYCN amplification in retinoblastoma is not known." (PMID 33270844, 2020).
small cell lung carcinoma (1 paper, 2018). Small cell lung cancer (SCLC) is a highly aggressive malignant neoplasm, accounting for 10-15% of lung cancer cases, characterized byrapid growth, and early metastasis. "MYCN opposite-strand (MYCNOS, N-CYM, MYCN-AS1, NYCM, CYMN) is produced by antisense transcription across exon 1 and intron 1 of MYCN that has been shown to be highly expressed in MYCN-amplified NB and small cell lung cancer." (PMID 29466962, 2018).
cancer (13 papers, 2014 to 2024). A tumor composed of atypical neoplastic, often pleomorphic cells that invade other tissues. "The risk signature of our study included 8 lncRNAs (CRNDE, LINC00844, FAM66C, TUBA3FP, SNHG8, HAR1A, LINC00641, and MYCNOS), and previous evidence has suggested that these lncRNAs are closely linked to the occurrence and development of cancer." (PMID 35832170, 2022). "In co-amplification with MYCN, MYCNOS may uniquely function only in MYCN-amplified tumors for cancer progression." (PMID 33270844, 2020). "However, lncRNAs reportedly play opposing roles in different cancers via crosstalks among multiple mechanisms; thus, the role of MYCNOS in SOC may require further investigation." (PMID 38895621, 2024). "It is known that MYCNOS lncRNA regulates the expression of MYCN by binding to its promoter and influencing cancer cell phenotype, but its role in the regulation of immune cells has not been indicated." (PMID 36294833, 2022). "MYCNOS-01 affects cell growth of MYCN-amplified RMS and NB and could also play a role in other MYCN-driven cancers." (PMID 29466962, 2018).
tumor (13 papers, 2004 to 2025). "The lncRNA, mycn opposite strand (MYCNOS) physically interacts with a transcription factor CCTF and epigenetically enhances MYCN expression resulting in loss of differentiation, tumor progression and invasion in NB cells." (PMID 27517149, 2016). "To date, three genes have been identified that are frequently co-amplified with MYCN in NBs: DDX1 in 50% of the cases, NAG in 20% of the tumours, and MYCNOS in all cases." (PMID 19615087, 2009). "Nevertheless, whether MYCNOS exerts a tumor-suppressive or tumor-promoting effect in SOC remains to be further investigated." (PMID 35585970, 2022). "Previous studies of MYCNOS-02 have identified its role in NB tumor growth and metastasis." (PMID 29466962, 2018). "Among the MNA tumors (n=10), five tumor suppressor genes (among other genes) were underexpressed within the distal 1p: CAMTA1, KIF1B, PRDM2, FABP3, and CDKN2C; whereas MYCNOS and MYCN were the two top differentially upregulated genes on 2p." (PMID 23656755, 2013). "MYCN-MB fusion transcripts were unique to each tumor; 2 recurrent fusion-partner genes, DDX1 and NBAS (immediately upstream of MYCN41) were involved in fusions with each other and additional partners (MYCNOS) in 3 MYCN-MBGrp3/4 tumors, but fusion position and gene order were not conserved." (PMID 39377358, 2025).
MYCNOS also shares sentences with these, for which no sentence is quoted: bladder cancer (3 papers); rhabdomyosarcoma (2); alveolar rhabdomyosarcoma (1); cardiovascular diseases (1); cholangiocarcinoma (1); Down syndrome (1); metastatic tumor (1); Nephroblastoma (1); pancreatic cancer (1); Sepsis (1); skin cutaneous melanoma (1).